LRRC31 (leucine rich repeat containing 31)
Synonyms: FLJ23259; HEL-S-293
Tractability: No criterion of Open Targets' tractability assessment is met for any kind of drug.
Gene: Protein-coding gene on chromosome 3 (169,837,917 to 169,870,000, reverse strand). Ensembl gene ENSG00000114248.
Subcellular location (Human Protein Atlas): Nucleoplasm; Cytosol
Genetic constraint (gnomAD): Loss-of-function variants: 34 observed, 45.5 expected, observed/expected ratio (o/e) 0.75, 90% interval 0.57 to 1. The upper end of that interval is the gene's LOEUF score, 1, which puts it in group 4 of 6, group 1 being the genes least tolerant of losing a copy. Missense variants: 606 observed, 647.22 expected, observed/expected ratio (o/e) 0.94, 90% interval 0.88 to 1. Synonymous variants: 235 observed, 242.97 expected, observed/expected ratio (o/e) 0.97, 90% interval 0.87 to 1.08.
Homologues: Orthologues: chimpanzee LRRC31 (99% identical), macaque LRRC31 (95% identical), dog LRRC31 (77% identical), pig LRRC31 (68% identical), rat Lrrc31 (62% identical), mouse Lrrc31 (62% identical), tropical clawed frog lrrc31 (46% identical), zebrafish lrrc31 (35% identical).
Diseases named in the same sentence as LRRC31 in open-access papers:
LRRC31 is named in the same sentence as 7 diseases in open-access papers, as found by Europe PMC text mining. Sharing a sentence is not in itself a finding about the gene and the disease. The quoted sentences say what the papers report.
breast carcinoma (3 papers, 2021 to 2023). "LRRC31 was found to act as a DNA repair inhibitor that sensitizes breast cancer brain metastasis to radiation which can be targeted for cancer radiosensitizing therapy." (PMID 36439479, 2022). "In addition, LRRC31 has been identified as a master regulator of the nonhomologous end‐joining mechanism and plays a central role in breast cancer radiotherapy." (PMID 38098610, 2023).
eosinophilia (1 paper, 2021). "In addition, the LRRC31 mRNA was positively correlated with eosinophilia and IL13 and IL5 expression, and was related to cellular immune regulation as well as inflammatory response." (PMID 34616724, 2021).
eosinophilic esophagitis (1 paper, 2023). Eosinophilic esophagitis (EoE) is a chronic, allergic disease of the esophagus characterized clinically by symptoms of esophageal dysfunction (including vomiting, dysphagia, feeding disorders, food impaction and abdominal pain) which persist after treatment with proton pump inhibitors (PPIs). "LRRC31, characterized by its nine leucine‐rich repeats, is induced by interleukin 13 to regulate esophageal epithelial barrier function in eosinophilic esophagitis." (PMID 38098610, 2023).
lung carcinoma (1 paper, 2023). "We employed qRT‐PCR and WB techniques to assess the expression of LRRC31 in various lung cancer cell lines, revealing that LRRC31 was expressed at lower levels across different lung cancer cell lines." (PMID 38098610, 2023).
cancer (3 papers, 2022 to 2024). A tumor composed of atypical neoplastic, often pleomorphic cells that invade other tissues. "LRRC31 was found to be a DNA repair suppressor that can target cancer radiation to increase sensitivity." (PMID 38750571, 2024).
LRRC31 also shares sentences with these, for which no sentence is quoted: lung adenocarcinoma (1 paper); tumor (1).